TRAPPC10 (trafficking protein particle complex subunit 10)
Description:
Specific subunit of the TRAPP (transport protein particle) II complex, a highly conserved vesicle tethering complex that functions in late Golgi trafficking as a membrane tether.
Synonyms: EHOC-1; EHOC1; TMEM1; TRS130; GT334; NEDMISS; TRS30
Tractability: PROTAC: ubiquitination databases record sites on it; its protein half-life has been measured.
Gene: Protein-coding gene on chromosome 21 (44,012,309 to 44,106,553, forward strand). Ensembl gene ENSG00000160218.
Subcellular location: Golgi apparatus, cis-Golgi network
Pathways (Reactome):
Vesicle-mediated transport: COPII-mediated vesicle transport; RAB GEFs exchange GTP for GDP on RABs
Gene Ontology:
Molecular function: protein binding; guanyl-nucleotide exchange factor activity
Biological process: intra-Golgi vesicle-mediated transport; early endosome to Golgi transport; endoplasmic reticulum to Golgi vesicle-mediated transport; vesicle coating; Golgi vesicle transport
Cellular component: TRAPP complex; cytoplasm; cytosol; TRAPPII protein complex; Golgi apparatus
Genetic constraint (gnomAD): Loss-of-function variants: 22 observed, 115.2 expected, observed/expected ratio (o/e) 0.19, 90% interval 0.14 to 0.27. The upper end of that interval is the gene's LOEUF score, 0.27, which puts it in group 1 of 6, group 1 being the genes least tolerant of losing a copy. Missense variants: 1,080 observed, 1,305.5 expected, observed/expected ratio (o/e) 0.83, 90% interval 0.79 to 0.87. Synonymous variants: 502 observed, 524.3 expected, observed/expected ratio (o/e) 0.96, 90% interval 0.89 to 1.03.
Homologues: Orthologues: chimpanzee TRAPPC10 (99% identical), macaque TRAPPC10 (99% identical), dog TRAPPC10 (91% identical), mouse Trappc10 (90% identical), rat Trappc10 (89% identical), guinea pig TRAPPC10 (87% identical), pig TRAPPC10 (87% identical), tropical clawed frog trappc10 (67% identical), zebrafish trappc10 (59% identical), Drosophila melanogaster SIDL (28% identical), Caenorhabditis elegans trpp-10 (19% identical).
Diseases named in the same sentence as TRAPPC10 in open-access papers:
TRAPPC10 is named in the same sentence as 12 diseases in open-access papers, as found by Europe PMC text mining. Sharing a sentence is not in itself a finding about the gene and the disease. The quoted sentences say what the papers report.
Intellectual disability (2 papers, 2011 to 2022). "Here, we define biallelic TRAPPC10 variants as a cause of a neurodevelopmental TRAPPopathy disorder, with core clinical features including microcephaly, severe global developmental delay and intellectual disability, short stature and pervasive behavioural abnormalities." (PMID 35298461, 2022). "In a similar experiment, we have further identified that the carboxyl terminus of TRAPPC9 is required for its interaction with TRAPPC2 and TRAPPC10, as deletional mutants of this domain found in some patients with intellectual disability failed to interact with TRAPPC2 or TRAPPC10." (PMID 21858081, 2011).
microcephaly (2 papers, 2022 to 2024). A congenital or acquired developmental disorder in which the circumference of the head is smaller than normal for the person's age and sex. "This suggests that in both humans and mice, TRAPPC10 deficiency-related microcephaly is predominantly due to the loss of white matter myelin biogenesis." (PMID 39769094, 2024). "The first report of pathogenic variants in TRAPPC10 was in patients with microcephaly, short stature, and speech delay who had an autosomal recessive homozygous missense variant NM_003274.5(TRAPPC10):c.2786C>T;p.(Pro929Leu), but no functional studies were conducted." (PMID 39769094, 2024). "While the families reported here did not have any recorded birth OFC measurements, there were no reports of affected children having noticably small head size at birth suggesting microcephaly associated with TRAPPC10-related disorder may be postnatal." (PMID 35298461, 2022). "We observed notable phenotypic overlap with Trappc10-/- mice which display microcephaly, reduced size of white matter brain structures with hypomyelination and skeletal involvement." (PMID 35298461, 2022). "Identification of further affected families will help clarify the nature of the microcephaly in TRAPPC10-related disorder, as with TRAPPC9-related disorder where this was also unclear initially." (PMID 35298461, 2022). "In human TRAPPC10-related disorder, microcephaly appears to be a relatively consistent feature, (8/10 individuals), as compared to ~60% of TRAPPC9 patients." (PMID 35298461, 2022). "Moreover, studies of Trappc10-/- knockout mice revealed neuroanatomical brain defects and microcephaly, paralleling findings seen in the human condition as well as in a Trappc9-/- mouse model." (PMID 35298461, 2022). "Similarly in mouse models, while the age of onset and progression of microcephaly is unclear, Trappc10-/- mice display more extensive brain size reduction and loss of white matter structures than Trappc9-/- mice." (PMID 35298461, 2022).
Obesity (2 papers, 2022 to 2024). Accumulation of substantial excess body fat. "However, patients bearing mutations of Trappc2, Trappc2l, Trappc4, Trappc6A/B, or Trappc10 do not develop obesity as patients with Trappc9 mutations do." (PMID 38889014, 2024). "Obesity is reported in ~50% of individuals with TRAPPC9-related disorder and is the only clincial feature not currently observed in individuals with TRAPPC10-related disorder." (PMID 35298461, 2022).
breast carcinoma (1 paper, 2019). "There was only one study to suggest the roles of TRAPPC10 until now and showed TRAPPC10 was an oncogenic driver to predict the poor prognosis for breast cancer patients, which seemed to be contrast with our results, implying TRAPPC10 may be a new tumor suppressor gene for LSCC." (PMID 31565549, 2019).
neurodevelopmental disorder (1 paper, 2022). A behavioral and cognitive disorder with onset during the developmental period that involves impaired or aberrant development of intellectual, motor, or social functions. "Rab18 has specifically been implicated in secretory pathway regulation, and RAB18 variants are associated with a neurodevelopmental disorder phenotypically overlapping TRAPPC10-related disorder." (PMID 35298461, 2022). "Together these studies confirm autosomal recessive TRAPPC10 variants as a cause of human disease and define TRAPP-mediated pathomolecular outcomes of importance to TRAPPC9 and TRAPPC10 mediated neurodevelopmental disorders in humans and mice." (PMID 35298461, 2022). "Studies of patient lymphoblastoid cells revealed an absence of TRAPPC10 alongside a concomitant absence of TRAPPC9, another key TRAPP II complex component associated with a clinically overlapping neurodevelopmental disorder." (PMID 35298461, 2022).
TRAPPC10 also shares sentences with these, for which no sentence is quoted: epilepsy (2 papers); holoprosencephaly (2); Tumor (2); cleft lip palate (1); congenital heart disease (1); developmental delay (1); glioblastoma (1).